KRT10-AS1 (KRT10 antisense RNA 1)
Synonyms: TMEM99; MGC21518
Gene: Long non-coding RNA gene on chromosome 17 (40,819,071 to 40,836,273, forward strand). Ensembl gene ENSG00000167920.
Subcellular location: Membrane
Diseases named in the same sentence as KRT10-AS1 in open-access papers:
KRT10-AS1 is named in the same sentence as 6 diseases in open-access papers, as found by Europe PMC text mining. Sharing a sentence is not in itself a finding about the gene and the disease.
KRT10-AS1 shares sentences with these, for which no sentence is quoted: cancer (2 papers); head and neck squamous cell carcinoma (1); lung adenocarcinoma (1); oropharyngeal squamous cell carcinoma (1); thyroid cancer (1); tumor (1).